BRCA1 (BRCA1 DNA repair associated)
Diseases named in the same sentence as BRCA1 in open-access papers (continued):
Sharing a sentence is not in itself a finding about the gene and the disease.
breast tumors (continued). "A strong association of these three independent genomic signatures with BRCA1/2 deficiency was found in 215 samples of breast tumors, regardless of the cancer subtype, demonstrating that they correlate with each other and that they all measure the same genomic alteration." (PMID 39220639, 2024). "To test whether the increased MDSC populations in Brca1-MT tissues could inhibit T cell proliferation, we cocultured MDSCs isolated from spleen, mammary gland, and breast tumor tissues from both WT and Brca1-MT mice with T cells from 2 months-old WT mice to monitor the T cells proliferation." (PMID 35304461, 2022). "Furthermore, in mouse and human breast tumors lacking BRCA1, satellite RNAs are highly expressed, as BRCA1 facilitates the monoubiquitination of histones associated with satellite DNA, thereby suppressing transcription." (PMID 32784923, 2020). "Finally, BRCA1 mRNA expression was strongly associated with high AHR-expressing breast tumors in the ERα-negative subpopulation (p = 0.0000023)." (PMID 29320557, 2018). "However, in a considerable number of human BRCA1/2 associated breast tumours, loss of heterozygosity (LOH) of the wild type allele is not observed." (PMID 29184099, 2017). "In addition, immunohistochemical analyses of IGF1R levels in a collection of primary breast tumors derived from BRCA1 mutation carriers and non-carriers revealed a higher score in BRCA1-associated tumors compared to sporadic tumors." (PMID 28706506, 2017). "Likewise, alterations in the concentrations of metabolites in cell pellets could provide new insights into the pathological heterogeneity of TN breast tumours and its relationship with BRCA1." (PMID 29259228, 2017). "One study showed that BRCA1 regulates the expression of CaSR in MCF-7 and MDA-MB-231 cells but it is not known whether breast tumors in patients with BRCA1 mutations have different levels of CaSR expression than non-BRCA1-associated tumors." (PMID 27746743, 2016). "Moreover, mammary-specific biallelic CtIP ablation did not elicit breast tumors in a manner reminiscent of BRCA1 loss." (PMID 27058754, 2016). "Finally, as pCR is rarely achieved by NCT in ER+ breast tumors, we searched if BRCA1 (Pro871Leu), ERCC1 (Asn118Asn), CYP1B1 (Leu432Val) and SLCO1B3 (IVS12-5676) could stand for predictive markers of NCT for patients with this subtype of tumor." (PMID 26180747, 2015). "Thus, a hypothesis may be proposed that the methylation status of BRCA1 promoter may be served as a biomarker for screening metastasis in breast tumors." (PMID 26643130, 2015). "We conclude that constitutive high expression of AhR associated with BRCA-1 gene hypermethylation may be prognostic markers of ERα-negative breast tumor development." (PMID 26715507, 2015). "Consistent with the postulate that mutant BRCA1 may lead to deregulated IGF1R expression, a recent immunohistochemical analysis revealed significantly elevated IGF1R levels in primary breast tumors derived from BRCA1 mutation carriers, compared to sporadic tumors." (PMID 24904527, 2014). "Furthermore BRCA1 mutant tumours more frequently overexpress HIF1α than sporadic breast tumours." (PMID 25010005, 2014). "BRCA1 mutations do not affect risk of bilateral breast tumors in Dutch high risk individuals." (PMID 24312913, 2013).
breast tumors (continued). "Collectively, we propose that BRCA1/p220 loss of expression or function triggers BRCA1-IRIS overexpression through a post-transcriptional mechanism, which in turn promotes formation of aggressive and invasive breast tumors by inducing expression of TN/BL and survival proteins." (PMID 22431556, 2012). "The growth rate of BRCA1/2-associated breast tumors is not accelerated." (PMID 22295226, 2011). "However, the breast tumours from older BRCA1 patients also differed from mutation-negative ones by their higher grade." (PMID 15987451, 2005). "CD109, AHNAK2, and MFGE8 in breast BRCA1-mut cancers, and B3GNT7, CTSV, and GSDMC in BRCA2-mut breast tumors." (PMID 40647506, 2025). "As observed in ovarian and breast tumours, targeting poly (ADP-ribose) polymerase 1 (PARP1) in tumours with BRCA1 and breast cancer gene 2 (BRCA2) inactivation selectively causes cancer cell death, showing promise in clinical settings." (PMID 39271762, 2024). "T. gondii transcriptionally regulates several signaling pathways by altering the hub genes such as BRCA1, MYC and IL-6, which can inhibit the breast tumor growth and migration, hinting at a potential therapeutic strategy." (PMID 38654350, 2024). "However, ERCC6L−/− and ERCC6L+/− mice did not develop mammary gland tumors, which suggested that ERCC6L knockout does not induce tumorigenesis alone and might not be a breast tumor susceptibility gene such as BRCA1/2." (PMID 37667329, 2023). "In agreement with the TCGA data, the degree of bi-allelic LoF was high; 96% for BRCA1 (both germline and somatic), 89 and 90% for BRCA2 (germline and somatic, respectively) in ovarian tumours and 86–91% and 75–86%, respectively, in breast tumours." (PMID 34979999, 2022). "The gene expression investigations revealed the substantial down-regulation of BRCA1 (P = 0.02), CHEK2 (P = < 0.0001), BRIP1 (P = < 0.0001), and RAD51 (P = 0.01) in breast tumors compared with adjacent normal tissues." (PMID 35715772, 2022). "A pilot study assessed the feasibility to measure the formation of BRCA1, FANCD2 and RAD51 foci after IR in small pieces of breast tumors ex vivo." (PMID 33670893, 2021). "Here, the results highlight the potential of PRMT1 as a clinical molecular target to modulate BRCA1 functions after IR and suggest that pharmacological inhibition of this protein or the use of hypomethylating treatments could be therapeutically useful for sensitizing breast tumors to radiotherapy." (PMID 32764667, 2020). "To define characteristic features of HRD tumors and analyze the correlations between BRCA1/BRCA2 and BC subtypes, we analyzed 981 breast tumors from the TCGA database using the signature analyzer." (PMID 32719318, 2020). "In summary, BECN1 is found to be deleted independently of BRCA1 in some ovarian and breast tumors, although the majority delete BECN1 and BRCA1 concomitantly." (PMID 31923184, 2020).
breast tumors (continued). "Global miRNA expression profiling using NanoString technology was performed on 43 hereditary breast tumors (15 BRCA1, 14 BRCA2, and 14 BRCAX), 23 sporadic breast tumors and 8 normal breast tissues." (PMID 32087690, 2020). "As expected, in our series, lower levels of both BRCA1 and ATM genes were observed in sporadic breast tumors in which higher expression of TGFB1 was observed." (PMID 28881597, 2017). "Other than BRCA1/2, CNV in other HR genes play a more important role to reduce HR pathway activity in sporadic breast tumors." (PMID 29146938, 2017). "Resveratrol, which binds and activates estrogen receptors, are important factor in the regulation of transcription of estrogen-responsive target genes and increases expression of BRCA1 and BRCA2 mRNA in breast tumor cell lines." (PMID 28674526, 2017). "BECN1 and BRCA1 were each deleted in approximately one-third of the breast tumors in both the TCGA and METABRIC datasets (BECN1 deletion in 34% in TCGA and 33% in METABRIC; BRCA1 deletion in 35% in TCGA and 27% in METABRIC)." (PMID 25825707, 2015). "TNBC exhibited increased basal AhR and BRCA-1 promoter CpG methylation compared to LUM-A, LUM-B, and HER-2-positive breast tumors." (PMID 26715507, 2015). "We further extended our studies of BRCA-1/AhR cross-talk to human breast tumors, and found that compared to LUM-A, LUM-B, and HER-2-positive tumors, TNBC had higher AhR and BRCA-1 CpG methylation." (PMID 26715507, 2015). "We demonstrated positive and significant correlations between BRCA1, ERα, PR, aromatase, and AKR1C3 mRNA expression in various subsets of breast tumors." (PMID 24223121, 2013). "We found concordant BRCA1 protein staining in frozen and FFPE tissue specimens of 22 randomly selected breast tumors." (PMID 23855721, 2013). "High BRCA1-IRIS expression was detected in the majority of human breast tumors analyzed, which was positively correlated with that of AKT1-, AKT2-, p-AKT-, survivin, but negatively with BRCA1/p220 expression." (PMID 22511931, 2012). "Taken together, these data show that the increase in BRCA1-IRIS expression correlates with enhanced aggressive breast tumor behavior and adverse outcomes, especially in patients with HER2+ or TN/BL breast tumor subtypes." (PMID 22511931, 2012). "In our study methylation of the BRCA1, APC and RASSF1A promoter regions was analyzed in 75 paired breast tumor and PB DNA samples using the MS-HRM (Methylation Sensitive High Resolution Melting) protocol." (PMID 22129206, 2011). "We have examined methylation status of the BRCA1, APC and RASSF1A promoter regions in a panel of 75 breast tumor and PB DNA samples from the same individual." (PMID 22129206, 2011). "BRCA1 and BRCA2 positive nuclear staining was observed in 6 (30%) and 9 (45%) out of 20 breast tumors, respectively." (PMID 20230646, 2010). "The purpose of this study was to examine the potential involvement of the BRCA1 and BRCA2 genes in sporadic breast tumour development." (PMID 19589159, 2009). "Our results confirm that AI at the BRCA1 and BRCA2 loci are common events in sporadic breast tumours, present in 37.4% (49/131) and 31.1% (42/135) of primary sporadic breast tumours, respectively." (PMID 16846527, 2006).
breast tumors (continued). "Genes whose products are known to interact with BRCA1 and/or BRCA2, or are down-regulated in breast tumours, are particularly attractive candidates, and can be prioritised for investigation." (PMID 16280053, 2005). "The most significant variation of BRCA1 expression was obtained in contact with the GFAP + PTX scaffold (p < 0.01), suggesting that the composition of GFAP promotes PTX activity with the highest efficiency in breast tumor cells." (PMID 39940603, 2025). "Moreover, patients with BRCA1/2- or PALB2 (partner and localizer of BRCA2)-mutant breast tumors that display heightened FLT1 expression in their tumor cells at pre-treatment are at high risk for progression on PARPi." (PMID 38956205, 2024). "Breast tumors with BRCA1/2 mutation carriers are more frequently HER2 negative, and triple-negative tumors (TNBC) account for approximately 68% of BRCA1 tumors." (PMID 37664050, 2023). "In some cases, breast tumors can exhibit both genetic defects and these Her2+/BRCA1 negative tumors tend to exhibit worse prognosis." (PMID 37627161, 2023). "In parallel to the cell viability results in murine 4T1 cell line, treatment with gene therapeutics (BRCA1 + NP and BRCA2 + NP) in syngeneic mouse model carrying 4T1-induced breast tumors, showed significant tumor regression pattern in comparison to the NP control group." (PMID 36631481, 2023). "Elevated levels of miR-155-5p were detected in patients with non-aggressive and localized breast tumors and in patients with late-stage aggressive ovarian tumors, as well as in CF BRCA1-methylation carriers." (PMID 37240365, 2023). "Previously, we have shown that low RECQL breast tumors were significantly associated with low PARP1, BRCA1 negative, low RAD51, low ATM, low nuclear pChk1, low nuclear Chk2, low XRCC1, low FEN1, low SMUG1, and low DNA-PKcs expression." (PMID 38134458, 2023). "BRCA1 controls the expression of miR-155 at the epigenetic level, which, in turn, directly regulates FOXO3a and RUNX2, affecting the metastatic potential of breast tumor cells." (PMID 36551878, 2022). "When compared with non-PV carriers, breast tumors from BRCA1 PV carriers expressed significantly lower ER (15.2% vs 78.2%, p < 0.001) and lower PR (6.8% vs 41.1%, p < 0.001) staining." (PMID 35135604, 2022). "In addition, in syngeneic mouse breast tumor models and xenotransplantation models, KDM5B knockout leads to upregulation of tumor suppressor genes such as BRCA1, CAV1, and HOXA5 and increased H3K4 methylation in the chromatin regions of these target genes." (PMID 35493099, 2022). "To investigate the effect of BRCA1+/− iMSCs on tumor growth and invasion in vivo, we assessed the activity of 4T1 breast tumor cells in the presence or absence of both types of iMSCs." (PMID 33513753, 2021). "BRCA1-mutant breast tumors, for example, are typically negative for estrogen receptor alpha (ER alpha)." (PMID 35008774, 2021). "We also observed that these miRNAs achieved slightly higher AUC values in BRCAX breast tumors compared to BRCA1 and BRCA2 breast tumors, suggesting that these miRNAs have higher specificity and specificity rates for hereditary BRCAX as compared to BRCA1/2-mutated breast tumors." (PMID 32087690, 2020). "This is the first study that investigates the prevalence of pathogenic RECQL germline variants in 302 BRCA1 and BRCA2 negative high-risk patients with ER positive and/or PR positive breast tumors from Pakistan." (PMID 33342430, 2020). "In order to explore whether miRNA expression profiling could also discriminate BRCA1, BRCA2, and BRCAX breast tumors, we performed a multiple comparison to identify a miRNA signature among HBC." (PMID 32087690, 2020).
breast tumors (continued). "Comprehensive RECQL variant analysis was performed in 302 BRCA1 and BRCA2 negative patients with ER and/or PR positive breast tumors using denaturing high-performance liquid chromatography followed by DNA sequencing." (PMID 33342430, 2020). "In summary, we identified a single pathogenic RECQL variant in 302 BRCA1 and BRCA2 negative high-risk patients with ER positive and/or PR positive breast tumors." (PMID 33342430, 2020). "Welcsh et al53 described the absence of BRCA1 expression in primary breast tumour cells without expression of STC1 and that BRCA‐1‐induced cells had a much higher expression level of STC1 compared with control cells." (PMID 32468698, 2020). "Tumors carrying mutations in the BRCA1 and BRCA2 genes, particularly in BRCA1, have more point mutations than sporadic breast tumors, which is not explained by their larger genome size owing to copy number alterations." (PMID 31182087, 2019). "The HRD scores in their 2014 study examined breast tumors representing TNBC and all ER/HER2 subtypes, and showed a significant association with BRCA1/2 deficiency regardless of subtype or stage." (PMID 30934991, 2019). "In contrast to breast tumors associated with BRCA1, lack of caveolin-1 expression in breast tumors has been reported in patients with germline mutations in BRCA2, suggesting that the expression of caveolin-1 occurs only in tumors with mutations in BRCA1." (PMID 31244284, 2019). "With the data presented here, we characterized a novel, non-genomic role for BRCA1 in breast tumour suppression, contributing to a growing list of emerging BRCA1 functions." (PMID 30323899, 2018). "The role of BRCA1, BRCA2, PRAB, and Erα genes as an oncogene responsible for the downregulation of the incidence of cancer progression is well established in a wide variety of tumors, including breast tumors." (PMID 28761624, 2017). "Overall, our findings highlight a critical role of Rak in the maintenance of genomic stability, at least in part, through protecting BRCA1 and provide novel treatment strategies for patients with breast tumors lacking Rak." (PMID 29156836, 2017). "Promoter methylation analysis of TCGA data showed that BRCA1 promoter methylation status in ovarian and breast tumors correlates with BRCA1 but not BRCA2 expression levels." (PMID 28831036, 2017). "Our previous analysis of a large cohort of breast tumor samples (n>500) showed that IRISOE correlates with lack of BRCA1 expression." (PMID 28052035, 2017). "RANK protein expression was absent or low (0 and 1+) in 74.5% of malignant breast tumors from BRCA1/2 WT patients, with intermediate (2+) expression detectable in 25.5% of cases." (PMID 27241552, 2016). "It is not clear how BRCA1 dysfunction can influence the level of miR-214 in ovarian and breast tumors as yet." (PMID 25705321, 2015). "The result demonstrated that the difference for the frequency of BRCA1 methylation between breast tumors and non-cancerous breast tissues group was smaller than that between cancers and normal breast tissues group." (PMID 26643130, 2015). "Finally, we document that human TNBC had higher AhR expression and BRCA-1 promoter CpG methylation compared to human luminal-A (LUM-A), LUM-B, and HER-2-positive breast tumors." (PMID 26715507, 2015). "Breast tumors lacking BRCA-1 tend to be triple-negative (TNBC) basal-like characterized by reduced expression of estrogen receptor-α (ERα), progesterone receptor (PR), and epidermal growth factor receptor-2 (HER-2)." (PMID 26715507, 2015). "Nevertheless, the connection between higher AhR expression and/or activation and BRCA-1 promoter hypermethylation in breast tumors has not been investigated." (PMID 26715507, 2015).